CDK4 (cyclin dependent kinase 4)
Diseases named in the same sentence as CDK4 in open-access papers (continued):
Sharing a sentence is not in itself a finding about the gene and the disease.
breast cancer (continued). "Palbociclib, a selective inhibitor of CDK4 and CDK6 developed by Pfizer (USA), was demonstrated to be effective in a phase III study involving 521 patients who had hormone-receptor-positive metastatic breast cancer, and FDA approved its application for breast cancer in February 201539,40." (PMID 33009370, 2020). "Although ER+/HER2+ breast cancers are not currently eligible for CDK4/6 inhibitor therapy, preclinical data have shown that cyclin D1/CDK4/6/pRB axis may be deregulated and represent a key mechanism driving resistance to anti-HER2 therapies." (PMID 32164162, 2020). "At present, endocrine therapy combined with CDK4/6 inhibitors has achieved significant therapeutic effects and controllable toxicity in many clinical trials and combined therapy has become the most promising therapeutic strategy for HR+/HER2− breast cancer patients." (PMID 32357912, 2020). "Furthermore, we investigated the impact of cyclin E overexpression on prognosis in four independent public mRNA expression data sets in HR-positive early breast cancer patients who did not receive CDK4/6 inhibitors." (PMID 33260316, 2020). "Other treatment possibilities include more targeted therapies—cyclin-dependent kinase 4 and 6 inhibitors (palbociclib, ribociclib, abemaciclib) that were recently approved by FDA in combination with hormone therapies for treatment of ER+ Her2- advanced breast cancer." (PMID 32947901, 2020). "The SYK inhibitor, BI 1002494, caused no increase in proliferation in breast cancer cells or primary mammary epithelial cells in 2D or 3D cultures, nor changes in proliferation (CD1/2, CDK4, PCNA, Ki67) or invadopodia markers (MMP14, PARP, phospho-vimentin Ser56)." (PMID 32292575, 2020). "An increasing number of novel drugs, including cyclin-dependent kinase 4/6 inhibitors, poly ADP-ribose polymerase inhibitors, and programmed death-ligand 1 inhibitors, have been shown to improve outcomes and have been recently approved for breast cancer treatment in the past few years." (PMID 32528870, 2020). "It is not difficult to conclude that the exploration of CDK4/6 inhibitors in other cancers except breast cancer, such as liposarcoma, lymphoma melanoma, and many other advanced cancers, is still at an early stage and is mostly limited to basic experiments and stage I or II clinical trials." (PMID 32357912, 2020). "The CDK4/6i used in the clinical practice are palbociclib, approved by the US Food and Drug Administration (FDA) in 2015 for the treatment of postmenopausal HR+/HER2− advanced breast cancer (ABC) in combination with hormone treatment (letrozole or fulvestrant); ribociclib; and abemaciclib." (PMID 32784518, 2020). "Cyclin-dependent kinase 4/6 (CDK4/6) inhibitors, which block the transition from the G1 to S phase of the cell cycle by interfering with Rb phosphorylation and E2F release, have shown potent antitumor activity and manageable toxicity in HR+/HER2− breast cancer patients." (PMID 32357912, 2020). "To date, three CDK4/6 inhibitors are approved against hormone receptor positive, human epidermal growth factor receptor 2 negative metastatic or advanced breast cancer in combination with aromatase inhibitors or fulvestrant both in first and subsequent lines of therapy." (PMID 32788596, 2020). "Moreover the combination of CDK4/6 inhibitor palbociclib and FDA-approved FGFR inhibitor erdafitinib showed a complete in vivo response in SCID/beige mice xenografted with estrogen receptor positive and FGFR1 amplified breast cancers." (PMID 32188012, 2020). "One study reported a correlation between the presence of active CDK4 and the palbociclib sensitivity in breast cancer cell lines and their tumor models, implying that CDK4/6 functions could not be identical." (PMID 31448056, 2019).
breast cancer (continued). "Three highly selective CDK4/6 inhibitors, palbociclib (PD-0332991), ribociclib (LEE001), and abemaciclib (LY2835219), have been recently approved by the FDA for treating ER+/HER2− advanced breast cancers, which are often characterized by dysregulated CDK4/6 activation." (PMID 30718512, 2019). "To determine whether naturally occurring FGFR1 amplification promotes resistance to fulvestrant plus CDK4/6 inhibitors, we selected three ER+/HER2− human breast cancer cell lines with FGFR1 gene amplification as determined by FISH: CAMA1, MDA-MB-134, and HC150015." (PMID 30914635, 2019). "Several potent, selective small-molecule inhibitors targeting CDK4/6 (CDK4/6is) have undergone clinical trials, including palbociclib (PD0332991), abemaciclib (LY-2835219) and ribociclib (LEE001), and gained regulatory approval in combination with hormonal therapy in breast cancer." (PMID 31296956, 2019). "Additionally, combined treatment with BZA and the CDK4/6 inhibitor palbociclib resulted in additional inhibitory potency of cellular proliferation in breast cancer cells expressing both WT and Y537S ERα without impacting BZA’s action." (PMID 30489256, 2018). "Thus, CDK4 and CDK6 represent valuable therapeutic targets of ER+ advanced breast cancer." (PMID 30518851, 2018). "Most mechanistic studies have been carried out in breast cancer cell lines, which are clonally selected, and since breast tumors are heterogeneous, we utilized two PDX tumor models to elucidate the role of transcriptionally functional ER in the CDK4/6 inhibitor response." (PMID 29963233, 2018). "When mice harboring mammary tumors overexpressing the ERBB2 gene were crossed with CDK4 knockout mice, the resulting littermates did not develop tumors, and the acute loss of cyclin D1 or CDK4 proteins mediated via RNA interference attenuated tumor growth." (PMID 30443290, 2018). "Moreover, ERα+ subtype shows the highest sensitivity to CDK inhibitors, possibly due to the hyperactivation of CDK4/6, while palbociclib showed no antiproliferative effect in Rb-deficient MDA-MB-468 (ERα−) human breast cancer cell lines." (PMID 28454587, 2017). "This might signify that CAAT shifts the cell cycle control in MDA MB 231 cells from a non-pRb-regulated to a pRb-regulated way, sensitizing the breast cancer cells to CDK4/6 inhibitory treatment." (PMID 28525384, 2017). "Inhibitors against cyclin-dependent kinase 4/6 (CDK4/6) are an important new class of agents with substantial antitumor activity in patients with advanced hormone receptor-positive (HR+) and human epidermal growth factor receptor 2-negative (HER2−) breast cancer." (PMID 29162134, 2017). "Specifically, Roniciclib selectively inhibits CDK2, not CDK4, in HR-NB but not in breast cancer, which results in new hypotheses regarding both CDK inhibition and cancer stem cell-like signatures." (PMID 28246384, 2017). "Except the currently used estrogen receptor status of breast cancers, no reliable biomarkers could be defined to diagnose tumors that depend on CDK4 activity and hence would respond to CDK4/6 inhibitors." (PMID 28566333, 2017). "We have found only little data concerning the effect of CDK4/6 inhibition in ER-negative breast cancers; a phase II study of palbociclib monotherapy in advanced heavily pretreated breast cancer recruited four cases with triple-negative disease, none of which experienced a response." (PMID 28528450, 2017). "Evidence from breast cancer mouse models suggests that Cyclin D1, and CDK4 and CDK6 activation contribute to suppressing senescence, as Cyclin D1 ablation in these models after tumor formation led to an onset of senescence in the isolated tumor cells, as did treatment with a CDK4 and CDK6 inhibitor." (PMID 29050219, 2017). "CDK4 expression correlated with a high signature score for a set of genes that predicts a high rate of distant recurrence in tamoxifen-treated patients with lymph node-negative, ER positive breast cancer." (PMID 27759034, 2016).
breast cancer (continued). "Palbociclib, the first selective CDK4/6 inhibitor introduced in the clinic has received FDA approval to combine with letrozole as first line therapy and to combine with fulvestrant after disease progression on prior hormonal therapy for patients with metastatic ER+ HER2- breast cancer." (PMID 27486754, 2016). "This group of patients (Rb1+, ER+) could be a target for CDK4/6 inhibition plus letrozole, with or without antiestrogen therapy, a regimen with proven efficacy in patients with advanced ER+ breast cancer." (PMID 26043844, 2015). "This study reports that rat mammary tumors induced with the AhR-agonist 7,12-dimethyl-benzo(a)anthracene (DMBA) had augmented CpG methylation of the Brca-1 gene; higher expression of Ahr, Cyp1b, and proliferation markers (Cdk4, Ccnd1); and diminished expression of BRCA-1 and ERα." (PMID 26715507, 2015). "Additionally, Nar altered the expression of apoptosis and cell-cycle regulatory genes by down-regulating Cdk4, Cdk6, Cdk7, Bcl2, x-IAP and c-IAP-2 and up-regulating p18, p19, p21, caspases 3, 7, 8 and 9, Bak, AIF and Bax in both colorectal and breast cancer cells." (PMID 26074733, 2015). "For example, cyclin D [which forms a complex with CDK4/6] was suggested to operate upstream of ER and to enhance transactivation through an estrogen response element in a CDK-independent manner, whose overexpression was shown to correlate with an ER-positive status in breast cancer." (PMID 25425654, 2014). "Our results also highlight the importance of HER-2/neu or PI3K/Akt components, including GSK-3β, β-catenin, cyclin D1, Cdk4, p21WAF1, and p27KIP1, which may serve as future targets for the development of therapeutic strategies against HER-2/neu-overexpressing breast cancer." (PMID 22701509, 2012). "Conversely, the effectiveness of everolimus plus exemestane on PIK3CA-mutant metastatic breast cancer (BC) after CDK4/6i failure has never been investigated in a prospective study." (PMID 41681940, 2026). "However, it appears that first-line treatment with endocrine therapy and CDK4/6 inhibitors in patients with ER+ and HER2- breast cancer is likely effective for the treatment of choroidal metastases secondary to ER+/HER2- breast cancer and may allow a delay in the use of local invasive interventions." (PMID 41959899, 2026). "In a preclinical study on breast cancer cells with acquired CDK4/6 inhibitor (CDK4/6i) resistance, authors discovered a collateral sensitivity towards the Wee-1 inhibitor adavosertib, which specifically depleted only CDK4/6i-resistant but not CDK4/6i-sensitive cells in a co-culture setting." (PMID 39915607, 2025). "However, for HR+/HER2− advanced breast cancer patients who progress under CDK4/6 inhibitor and endocrine therapy, there is no standard treatment recommended at the category 1 level in international guidelines, unless there is a positive mutation analysis result." (PMID 41156245, 2025). "However, direct comparisons between the three inhibitors combined with ET and a single CDK4/6 inhibitor or ET, as well as between the three inhibitors combined with ET, are still lacking, which hinders the selection of clinical drugs for HR+/HER2-breast cancer patients." (PMID 38832268, 2024). "Therefore, our study used the non-PH model to conduct NMA on the effectiveness of CDK4/6 inhibitors in the first-line treatment of HR + advanced breast cancer, and directly used survival time instead of HR as an efficacy indicator to more intuitively express the results." (PMID 39161906, 2024). "Of note, palbociclib, a selective CDK4/6 inhibitor (CDK4/6i), in combination with endocrine therapy, represents the first-line treatment for metastatic postmenopausal patients with estrogen receptor-positive and Her2 (Human epidermal growth factor receptor 2)-negative breast cancer." (PMID 39456957, 2024).
breast cancer (continued). "Cyclin-dependent kinase 4 and 6 inhibitors (CDK4/6i) have been approved in combination with endocrine therapy (ET) to treat estrogen receptor-positive (ER+) metastatic breast cancer (BC)." (PMID 37258566, 2023). "Thus far, CDK4/6 inhibitors (CDK4/6i) have proved the most promising, with three inhibitors (palbociclib, ribociclib, and abemaciclib) currently approved by the U.S. Food and Drug Administration (FDA) for oestrogen receptor (ER)-positive breast cancer treatment." (PMID 35568739, 2022). "This trend suggests that PLK1 could be a potential direct or indirect therapeutic target in HR-positive breast cancer even though the gene expression analyses of the current study were derived from breast cancer cohorts that were not exposed to CDK4/6 inhibitors." (PMID 35008374, 2022). "In spite of the fact that the mechanism is not fully defined, the lessons learned from Cyclin D1 and Cdk4 null mouse models have important implications with respect to therapeutic modalities that might be effective in the treatment of breast cancers that are HER2-positive." (PMID 36051751, 2022). "Similarly, prospective clinical trials also confirmed that the CDK4/6 inhibitor, palbociclib, the mTOR inhibitor, everolimus, and the PI3K inhibitor, buparlisib may improve progression-free survival (PFS) in patients with advanced breast cancer." (PMID 35317849, 2022). "Other reports also suggest that premalignant senescent cells induced by CDK4/6 inhibition do not acquire pro‐tumorigenic and detrimental properties in patients with breast cancer patients, suggesting that these effects could be beneficial for senescence surveillance." (PMID 35674109, 2022). "Based on the prevalence of FGFR alterations in breast cancer and their relevance during resistance to CDK4/6 inhibition targeting aberrant FGFR activity may hold clinical value for treating therapy-resistant BC." (PMID 33535617, 2021). "In addition, strategies to maintain cancer cell dormancy, including estrogen antagonists, inhibition of CDK4/6, ERK, and integrin signaling, may prevent reactivation of dormant cancer cells and tumor relapse, as shown by an acceptable clinical response in breast cancer." (PMID 34685686, 2021). "Clinical relevance that cyclin E-CDK2 signaling could be a therapeutic target is more strengthened by our analysis of the public gene expression profiling data sets from HR-positive breast cancer patients, even though they were not exposed to CDK4/6 inhibitors." (PMID 33260316, 2020). "This is a hypothesis that we will be testing in a major new national adjuvant trial, POETIC-A, in which patients with early ER+ breast cancer whose tumour continues to show high Ki67 expression after 2 weeks AI will be randomised to additional CDK4/6 inhibition or not." (PMID 31892336, 2019). "In addition, CDK4/cyclin D inhibition may be additionally beneficial for the treatment of human epidermal growth factor receptor 2 (HER2) and RAS‐driven breast cancers and potentially many other cancers because cyclin D1 displays most frequent somatic copy number aberrations of all cancer genes." (PMID 29669860, 2018). "Additionally, while not necessary for normal mammary gland development, CDK4 and cyclin D1 are required for induction of breast malignancies in mouse models, suggesting that CDK4 inhibition may inhibit breast cancer cells while sparing healthy tissues." (PMID 26857361, 2016). "Importantly, Cdk4 inhibition abrogates CA without significantly interfering with the cell cycle, suggesting that a unique function of Cdk4 is to signal CA in a subset of Her2+ breast cancer cells." (PMID 23776583, 2013). "Dalpiciclib is a cyclin-dependent kinase 4/6 (CDK4/6) inhibitor that plays a key role in hormone receptor (HR)-positive, human epidermal growth factor receptor 2 (HER-2)-negative breast cancer." (PMID 41930135, 2026).
breast cancer (continued). "New drugs, such as cyclin-dependent kinase 4/6 inhibitors (CDKIs), increase the life expectancy of receptor-positive (HR+) and human epidermal growth factor receptor 2 negative (HER2-) breast cancer patients." (PMID 41462352, 2025). "Ribociclib is one of the cyclin-dependent kinase 4 and 6 inhibitors (whose molecular formula is C23H30N8O3) approved by the FDA for the treatment of metastatic or advanced breast cancer with positive hormone receptors and HER-2 negative." (PMID 40075608, 2025). "Our results clearly demonstrated that CDK4/6 inhibitors plus endocrine therapy had a substantial positive impact on both PFS and OS in patients with HR+/HER2- breast cancer and had no heterogeneity compared with endocrine therapy alone." (PMID 40104496, 2025). "At present, there is evidence that highly selective small molecule inhibitors of CDK4 and CDK6, Palbociclib, Ribociclib and Abemaciclib, are effective in the treatment of breast cancer, but the therapeutic effect of prostate cancer is not clear." (PMID 39917165, 2025). "Of interest, upregulation of glutaminolysis as an adaptive mechanism is not limited as a survival response to CDK4/6i’s, having also been observed in response to other chemotherapeutic pressures, such as PARP inhibitors in breast cancer cells." (PMID 40696167, 2025). "Cyclin-dependent kinase 4 and 6 inhibitors (CDK4/6i) have changed the therapeutic paradigm of hormone receptor (HR) positive, human epidermal growth factor receptor 2 (HER2) negative advanced breast cancer (ABC)." (PMID 38242689, 2024). "First, the effects of CDK4/6 inhibitors and endocrine therapy separately on the HER2 pathway in HR+/HER2-low breast cancer were not examined." (PMID 39730704, 2024). "Abemaciclib, a cyclin-dependent kinase 4/6 (CDK4/6) inhibitor used for hormone-receptor-positive and human epidermal growth factor receptor 2 (HER-2)-negative breast cancer, can lead to elevated serum creatinine without implications on the true renal function." (PMID 39318897, 2024). "To date, there are no studies examining the feasibility of a combination of CDK4/6 inhibitor palbociclib with an RRM2 inhibitor for treating both ER+ and ER− palbociclib-resistant breast cancers." (PMID 38473336, 2024). "Implementation of CDK4/6 inhibitors (CDK4/6i) into clinical routine has revolutionized the treatment of patients with hormone receptor positive, HER2 negative advanced breast cancer (HR+/HER2− ABC)." (PMID 36876172, 2023). "The recent development of cyclin-dependent kinase 4/6 (CDK4/6) inhibitors, such as ribociclib, has considerably improved the management of hormone receptor positive (HR+) and HER2 negative (HER2-) advanced breast cancer." (PMID 38046373, 2023). "The current standard of care for HR‐positive, HER2‐negative advanced breast cancer (ABC) involves endocrine therapy, with or without cyclin‐dependent kinase 4/6 (CDK4/6) inhibitors." (PMID 38037839, 2023). "Pharmacologic inhibitors of CDK4/6 have shown significant clinical prospects in treating hormone receptor-positive and human epidermal growth factor receptor-negative (HR + /HER2-) breast cancer (BC) patients." (PMID 38037159, 2023). "Currently, combining CDK4/6 inhibitors with hormonal treatments is indicated for hormone receptor positive, HER2 negative breast cancer." (PMID 36123435, 2022). "CDK4/CDK6 inhibitors, which are well established for the treatment of breast cancer, have not previously been analyzed in the context of SM." (PMID 35804842, 2022). "Though not specifically analyzing ER+ breast cancer, one study using patient-derived xenografts (PDX) of melanoma to analyze resistance to CDK4/6 inhibitors determined that the PI3K–AKT pathway was activated in the intrinsically resistant models." (PMID 34830174, 2021). "Combination treatment with MIR9 and CDK4/6 inhibitor ribociclib synergized in luminal and HER2-positive breast cancer cell lines, although the interaction failed to reach statistical significance." (PMID 34439268, 2021).